MTOR (mechanistic target of rapamycin kinase)
Diseases named in the same sentence as MTOR in open-access papers (continued):
Sharing a sentence is not in itself a finding about the gene and the disease.
Obesity (continued). "However, data are very limited on the association between obesity phenotypes and mTOR pathway activation in breast tumors." (PMID 33024820, 2020). "In pathological states, increased activity of the mTOR signaling has been associated with obesity and, accordingly, the knockout mice for the mTOR downstream S6kinase 1 are protected against diet-induced obesity." (PMID 32784967, 2020). "Since this pathway regulates many major cellular processes and mTOR overactivation has been implicated in various health disorders including aging, obesity, type 2 diabetes, and also acne, recently several studies have been dedicated to developing drugs that can target this enzyme." (PMID 34466486, 2019). "The crosstalk between MAPK/ERK and Akt-mTOR signaling in adipocytes may predict an increasing risk of obesity related to adipogenesis/lipogenesis, insulin resistance and production of inflammatory cytokines." (PMID 30621146, 2019). "By extension, these observations suggest a potential link between obesity-induced increases in mTOR pathway activation and recurrence risk that could provide a rationale for the therapeutic use of mTOR inhibitors to prevent recurrence." (PMID 30867005, 2019). "Our previous experimental studies found that the promoter region of the Tsc1 gene in rat hypothalamus appeared to be at a high methylation state and its downstream mTOR gene expression was upregulated, thereby increasing appetite and food intake and finally causing obesity." (PMID 29853949, 2018). "The mTOR pathway is at metabolic confluence with the nutrient-hormonal signaling network and integrates with the energy status of cells, therefore, its dysregulation has been implicated in the development of obesity." (PMID 29329236, 2018). "From these studies, it appears that anti-inflammatory agents targeting PI3K, AKT, and mTOR could be a favorable option in the treatment of obesity-associated inflammation and cancer." (PMID 24904823, 2014). "Contrary to our hypothesis, diet‐induced obesity in pregnant mice was associated with inhibition of placental mTOR signaling." (PMID 24744907, 2014). "The situation is further complicated by the fact that obesity itself can result in chronic activation of mTOR, which has been linked to obesity-associated cancer, beta cell adaptation preceding type II diabetes, nonalcoholic fatty liver diseases, and other complications." (PMID 24379984, 2013). "Indeed, mice with adipose-specific loss of the mTORC1 are lean and resistant to HFD-induced obesity, while chronic pharmacological inhibition of mTOR by its specific inhibitor rapamycin exhibited anti-obesity effects in HFD mice." (PMID 24376752, 2013). "Data from various F2 mouse crosses also show that mTOR is causal for obesity traits." (PMID 19203388, 2009). "Overall, these data indicate that mTOR plays an important role in renal metabolic disease in obese SSLepRmutant rats before puberty and suggest that rapamycin might prevent renal hyperfiltration associated with obesity by decreasing renal SGLT2 activity." (PMID 41146401, 2025). "High BCAA levels have been implicated in the activation of the mammalian target of rapamycin (mTOR) signaling pathway, leading to oxidative stress, mitochondrial dysfunction and cell apoptosis, mechanisms that potentially contribute to the pathophysiology of obesity and related diseases." (PMID 39330498, 2024). "Furthermore, previous studies have revealed the association between obesity and the mTOR pathway." (PMID 33491531, 2021). "However, in contrast to our hypothesis, diet‐induced obesity was associated with an inhibition of placental mTOR signaling." (PMID 24744907, 2014).
Obesity (continued). "In parallel, obesity modifies drug disposition at every pharmacokinetic step, expanding the distribution volume for lipophilic agents such as calcineurin and mTOR inhibitors, altering CYP3A metabolism, and increasing interindividual variability in exposure." (PMID 42199481, 2026). "In this review, we summarize how intracellular metabolic pathways and master regulators, such as mTOR and AMPK, orchestrate immune cell function and how their dysregulation contributes to obesity-associated immune and metabolic dysfunction." (PMID 42083504, 2026). "Beyond linear activation, mTOR operates within multilayered regulatory networks shaped by metabolic and stress signals that are common in obesity and PCOS." (PMID 41301707, 2025). "This integrated ER↔mTOR circuit helps explain the heightened estrogenic vulnerability of the endometrium in obesity and provides mechanistic support for combinatorial targeting of ER and mTOR pathways in EIN and early EC." (PMID 41301707, 2025). "First, in obesity, chronic exposure to leptin and nutrient surpluses leads to persistent activation of the mammalian target of rapamycin (mTOR) signalling pathway in T cells, disrupting normal T cell receptor (TCR)-mediated signalling." (PMID 40553147, 2025). "Cardiometabolic diseases, including hyper-tension, obesity, type 2 diabetes, and dyslipidemia, share common molecular pathways, and mammalian target of rapamycin (mTOR) is a pharmacological target for improving metabolic and cardiovascular outcomes." (PMID 41406476, 2025). "Through alternative splicing, Sam68 maintains the level of mammalian target of rapamycin (mTOR) transcripts; Sam68−/− mice have lower mTORC1/mTORC1 activity and fewer pericytes in white adipose tissue, protecting them against dietary-induced obesity." (PMID 40732992, 2025). "Elevated branched‐chain amino acids (BCAAs) contribute to obesity and related diseases by promoting apoptosis, oxidative stress, mitochondrial dysfunction, and activating the mTOR signaling pathway." (PMID 40551726, 2025). "Firstly, a biased screening approach was taken where the metabolic pathways related to obesity were selected (FoxO, mTOR, cAMP, PI3K-Akt, insulin, adipocytokine, and Toll-like receptor)." (PMID 40981068, 2025). "From the myocardial cell metabolism perspective, in obesity, high cardiac load prompts myocardial cells to increase protein synthesis by signaling pathways such as the mammalian target of rapamycin (mTOR) pathway, leading to hypertrophy and increased LV mass." (PMID 40161389, 2025). "The activation of PI3K/AKT/mTOR signaling pathway in obesity induces hepatic steatosis and accumulation of visceral fat, further promoting liver and systemic inflammation." (PMID 40863244, 2025). "One in vivo study demonstrated that rapamycin, an mTOR inhibitor, reduces food intake and fat mass in diet-induced obesity (DIO) mice." (PMID 40299431, 2025). "In contrast, obesity can inhibit tumor immunity by suppressing mTOR-mediated glycolysis through excessive accumulation of FA." (PMID 40868150, 2025). "SRPK2 mediates SGs formation in obesity‐related pancreatic ductal adenocarcinoma (PDAC) by activating the IGF1/PI3K/mTOR/S6K1 pathway." (PMID 40211955, 2025). "Obesity is closely linked to insulin resistance, which significantly disrupts DDR mechanisms through dysregulation of the PI3K/AKT/mTOR signaling pathway." (PMID 40282189, 2025). "The mTOR signaling cascade represents a critical convergence point for obesity-related metabolic and hormonal perturbations in endometrial tissue." (PMID 41301707, 2025). "Obesity-associated aberrant PPAR expressions, promotes increased NK cell lipid uptake and accumulation, which inhibits mTOR pathway, c-Myc expression inducing NK cell dysfunctions." (PMID 40696355, 2025). "The relationship between vitamin D, AMPK, mTOR, and obesity involves intricate molecular interactions that regulate energy metabolism and adiposity." (PMID 40076782, 2025).
Obesity (continued). "Obesity-associated signaling pathways, such as Wnt/β-catenin, PI3K/AKT/mTOR, NOTCH, and JAK/STAT3 signaling pathways, are involved in immunotherapy resistance." (PMID 40863244, 2025). "Several key signaling pathways, such as PI3K/AKT/mTOR, NOTCH, and HIF-1α signaling pathways, are involved in obesity-associated cancer development and progression." (PMID 40863244, 2025). "mTOR regulates insulin signaling via IRS1 in metabolic tissues and is implicated in diseases like type 2 diabetes, obesity, and cancer." (PMID 40243885, 2025). "Through its interaction with mTOR, vitamin D reduces chronic inflammation, which is a key driver of obesity-related metabolic diseases." (PMID 40076782, 2025). "In obesity, under conditions of excess energy, mTOR enhances the transcriptional activity of PPARγ and increases the synthesis of proteins involved in lipid metabolism, such as lipoprotein lipase (LPL) and glycerol kinase (GyK)." (PMID 41287647, 2025). "Excessive food intake and obesity activate the mTOR (mechanistic target of rapamycin) pathway through the PI3K/Akt and IGF-I signaling pathways, along with AMPK." (PMID 39339816, 2024). "Dysregulation of the mechanistic target of rapamycin (mTOR) has been related to several metabolic conditions, notably obesity and type 2 diabetes (T2DM)." (PMID 39261960, 2024). "The mTOR signaling pathway is implicated in several pathological conditions, including T2DM and obesity." (PMID 39728125, 2024). "Elevated levels of leptin, a hormone associated with obesity, promote glycolysis in CD8+ T cells via the PI3K/Akt/mTOR pathway, exacerbating chronic inflammation linked to obesity." (PMID 39000296, 2024). "Several of the high-scoring genes (score ≥ 11) are known to be implicated in obesity (such as DGKI [score: 22.8], MC4R [19.6], BDNF [19.6], MTOR [16.8], SH2B1 [14.8], GIPR [14.3], AKT3 [11.6], and LEPR [11.6])." (PMID 38754426, 2024). "An in vitro study involving obese rats revealed that obesity triggers chronic excessive activation of mTOR activity in multiple tissues, consistent with the broader concept of nutritional sufficiency in regulating mTOR signalling activity." (PMID 38483608, 2024). "A recent study demonstrated that TMAO exacerbated sarcopenic obesity development through ROS-AKT/mTOR signaling in aged mice fed a high-fat diet." (PMID 38982486, 2024). "The proteins, mTOR, S6K, PPARγ, and C/EBPα, are considered to be essential for the treatment of obesity, and these are negatively regulated by AMPK." (PMID 38327997, 2024). "In the present study, we demonstrated that targeted induction of mTOR regulation in the liver by CePA synergistically ameliorated obesity, inflammation, and MASH." (PMID 39873005, 2024). "In this sense, there is great interest in developing mTOR inhibitors as therapeutic drugs for obesity and diabetes." (PMID 39728125, 2024). "Obesity and hyperlipidemia in the setting of adverse social determinants negatively impact NK cells via a pathway involving DUSP1/mTOR/TFEB, contributing to increased heart disease risk." (PMID 39718832, 2024). "To explore the potential importance of the mTOR/TFEB/LAMP1 axis in NK cells isolated from individuals W/O or WO/O obesity, we performed RT-qPCR analysis and Western blotting analysis." (PMID 39718832, 2024). "Hyperlipidemia, peroxisome proliferator-activated receptor (PPAR) alpha/delta agonist drugs, butyrate, and other metabolic changes in obesity reduce the function of mammalian target of rapamycin (mTOR) and NK cytotoxicity in vivo and in vitro." (PMID 39483457, 2024). "In summary, we demonstrate that hepatocyte-specific Wnt1 overexpressing mice fed by HFD develop hepatic steatosis and obesity accompanied by increased lipogenesis and disrupted β-oxidation as well as augmented Akt/mTOR signaling." (PMID 38152126, 2023). "Particularly, obesity and type 2 diabetes results in mTOR hyperexpression in various tissues, including PBMC." (PMID 37280548, 2023).
Obesity (continued). "Beyond the scope of this review are gestational diabetes, obesity treated with bariatric surgery and the treatment of renal allograft recipients with mTOR inhibition who received the SARS-CoV-2 mRNA BNT 162 bz (Pfizer BioNTech) vaccine." (PMID 37759585, 2023). "Long-term high-fat, high-sugar diets, obesity, and nutrient excess activated mTOR, which activated its downstream effector proteins, P70 ribosomal protein S6 kinase 1 (p70S6K1) and eukaryotic translation initiation factor 4E-binding protein 1 (4E-BP1)." (PMID 37898776, 2023). "Obesity-related accumulation of BCAA in plasma has been reported to interfere with the insulin signaling via activation of the mammalian target of rapamycin (mTOR) pathway, precisely the complex mTOR/p70S6K, with leucine as the most potent mTOR activator." (PMID 36771236, 2023). "Given the central role of mTOR signaling in metabolism and obesity, we decided to investigate the functional importance of Minar2 interaction with Raptor and its implication in mTOR signaling." (PMID 37245847, 2023). "In women with obesity delivering overgrown babies, there is hyperactivation of the mTOR pathway and elevated amino acid transporter levels in the placenta." (PMID 36484327, 2023). "One major cellular signaling pathway stimulated in women with obesity is the PI3K/Akt/mammalian target of rapamycin (mTOR) pathway." (PMID 37512149, 2023). "This part of the review will summarize the studies describing the role of mTOR signaling in obesity and systemic metabolism, with a focus on the adipose tissue and the neuronal control of food intake." (PMID 37511253, 2023). "mTOR signaling is also thought to play a key role in the development of metabolic diseases such as obesity." (PMID 36501200, 2022). "mTOR, as a key target to control energy metabolism, is an important protein for preventing and improving obesity." (PMID 36501200, 2022). "Previous research indicates that obesity can trigger a chronic excessive activation of mTOR activity in multiple tissues." (PMID 36501200, 2022). "All data suggest that mTOR is a vital target of polyphenols and plays a very important role in obesity prevention." (PMID 36501200, 2022). "AMPK chronic activity leads to the promotion of hyperphagia and obesity, while mTOR inhibition decreases the Ghre orexigenic function." (PMID 36362220, 2022). "In order to prevent obesity, the molecular mechanisms by which dietary polyphenols target the mTOR signaling pathway were examined." (PMID 36501200, 2022). "The function of dietary polyphenols and mTOR signaling in the prevention of obesity was systematically summarized in this paper." (PMID 36501200, 2022). "AMPK also decreases the expression of mTOR, the factor that phosphorylates the mTOR-p70S6K pathway and is activated in obesity." (PMID 36145056, 2022). "Polyphenols targeting mTOR modulate inflammation, insulin resistance, and so on, which means that polyphenols affect obesity through the gut–liver–brain axis by targeting mTOR." (PMID 36501200, 2022). "A further in vitro study investigated the PI3K/AKT/mTOR pathway to understand the mechanism of the anti-obesity effects identified in the in vivo study." (PMID 35268062, 2022). "The obesity mouse model resembles the changes in placental mTOR signalling and amino acid transporters activity observed in obese women giving birth to large babies." (PMID 35884994, 2022). "GRP78 and Akt form a positive feedback loop, and continuous overexpression of mTOR can further enhance triglyceride synthesis and obesity." (PMID 36498048, 2022). "In particular, characterizing the molecular fingerprint of obesity-related ADEVs can provide a bigger picture that better reflects metabolic adaptation though PI3K/Akt/mTOR." (PMID 35681526, 2022). "Mechanistically, polyphenols can target multiple signaling pathways and gut microbiota to regulate the mTOR signaling pathway to exert anti-obesity effects." (PMID 36501200, 2022).
Obesity (continued). "Diet induced obesity modulates important metabolism and cell survival proteins such as Akt and mTOR." (PMID 36117462, 2022). "The E2F family of transcription factors is implicated in the regulation of energy metabolism, adipose tissue, obesity and growth in general and our results from starved and mTOR-inhibited cells fit this picture well." (PMID 36271102, 2022). "The dysregulation of mTOR occurs in many pathological conditions, including type 2 diabetes, aging, cancer, and obesity." (PMID 36501200, 2022). "Experimental studies suggested that obesity and overnutrition activate mTOR in various tissues in islets of humans." (PMID 35528246, 2022). "Other immunological alterations related to obesity are decreased circulating lymphocyte populations and the hyperactivation of the mTOR protein in immune cells, which favors an increased activation of effector cells, compromising memory lymphocytes production." (PMID 35335046, 2022). "Studies have found that various diseases, such as cancer, obesity, type II diabetes, muscle diseases, and neurodegenerative diseases, are related to the abnormal expression or dysfunction of mTOR." (PMID 36014530, 2022). "Previous studies have shown that the activated mTOR/S6K1 signaling pathway inhibits the pathogenesis of obesity." (PMID 36230357, 2022). "In this review, we systematically summarized the research progress of polyphenols in preventing obesity through the mTOR signaling pathway." (PMID 36501200, 2022). "In summary, our results showed that EMPA activates Sestrin2-mediated AMPK/mTOR pathway and ameliorates lipid accumulation in obesity-related nonalcoholic fatty liver disease." (PMID 36133815, 2022). "Further research found potential mitophagy mediation by GRP78 through the AMPK/mTOR signaling pathway, which leads to that energy intake exceeding expenditure and obesity." (PMID 36498048, 2022). "There is a well-established observation that obesity and nutrient oversupply increase mTOR signaling in multiple cell types and organs." (PMID 36586433, 2022). "During the development of obesity, imbalanced food intake and energy expenditure lead to alteration of autophagy due to mTOR signalling." (PMID 35184387, 2022). "As a key kinase regulating the metabolic pathways in cells, the dysregulation of signaling through mTOR occurs in a variety of human diseases, including cancer, obesity, type II diabetes, immune diseases, and neurodegenerative diseases." (PMID 36014530, 2022). "Another study reported that hepatic mTOR activation in obesity led to the phosphorylation of cytosolic CRTC2 at Ser136, which in turn elicited SREBP1 processing and increased hepatic lipogenesis without any apparent changes in CRTC2 cell localization." (PMID 35428325, 2022). "Overall, dietary polyphenols targeting mTOR signaling in the prevention of obesity is beneficial for humans; however, the specific mechanism remains to be further explored." (PMID 36501200, 2022). "A possible major target for the prevention and treatment of obesity is mTOR because of its central involvement in cell growth and proliferation." (PMID 36501200, 2022). "Enhanced placental mTOR activity has been reported in the placenta of bigger babies born to women with obesity or GDM during pregnancy." (PMID 34032632, 2021). "Abnormalities in the mTOR pathway have attracted increasing attention and have been identified in many diseases, including cancer, obesity, type II diabetes mellitus, neurological and psychiatric diseases, neurodegeneration, and brain tumors." (PMID 34348681, 2021). "This work builds on prior studies which have explored targeting the mTOR pathway to prevent or reduce obesity in rodents, with mixed results." (PMID 35822052, 2021). "Direct mTOR deletion in the placenta resulted in offspring with obesity outcomes that were different between sexes." (PMID 34828683, 2021).